MIR663AHG (MIR663A host gene)
Synonyms: RP3-410C9.1; LOC124904967
Gene: Long non-coding RNA gene on chromosome 20 (26,167,816 to 26,251,546, reverse strand). Ensembl gene ENSG00000227195.
Gene Ontology:
Biological process: miRNA-mediated post-transcriptional gene silencing
Diseases named in the same sentence as MIR663AHG in open-access papers:
MIR663AHG is named in the same sentence as 4 diseases in open-access papers, as found by Europe PMC text mining. Sharing a sentence is not in itself a finding about the gene and the disease. The quoted sentences say what the papers report.
adenoma (1 paper, 2024). A neoplasm arising from the epithelium. "Noteworthy, the numbers of RNA interactors of some MP-RNAs (WDR62, TGFBR3, RN7SL5P, RMRP, MIR663AHG, AJ009632.2, CDKL1, OPRD1, PLOD1, AL117692.1, ATP13A2, EPB41) in cancer tissue were significantly increased compared with that in paracancer and adenoma." (PMID 38773399, 2024).
colon cancer (1 paper, 2023). "Additionally, MIR663AHG has been found to be downregulated in psoriatic tissues and acts as a tumor suppressor, inhibiting the development of colon cancer by cis-binding to miR663a/pre-miR663a." (PMID 37834450, 2023).
MIR663AHG also shares sentences with these, for which no sentence is quoted: tumor (2 papers); cancer (1).